HIF1A (hypoxia inducible factor 1 subunit alpha)
Diseases named in the same sentence as HIF1A in open-access papers (continued):
Sharing a sentence is not in itself a finding about the gene and the disease.
glioma (continued). "Furthermore, hypoxia‐inducible factor 1 alfa (HIF1α) which is expressed by glioma cells in response to oxygen‐depleted conditions, induces Treg migration into the TME of GBMs." (PMID 36776000, 2023). "The role of hypoxia resulting in HIF-1α in glioma migration is well recognized." (PMID 36334237, 2023). "This upregulation stabilizes lncRNA OIP5-AS1, which in turn, binds to miR-495-3p and decreases the association of miR-495-3p, hypoxia-inducible factor 1 alpha (HIF1A), and matrix metalloproteinase 14 (MMP14) mRNA, ultimately promoting the formation of vasculogenic mimicry in glioma." (PMID 37391814, 2023). "Third, the relationship among LINC02774, PHD3, and HIF‐1α should be demonstrated in glioma tissue." (PMID 37701531, 2023). "It was observed in human glioma cells that hypoxia induces PD-L1 upregulation in an HIF-1α-dependent manner, and it was further found in a murine glioma model that the combination of HIF-1α inhibitor and anti-PD-L1 antibody can improve the activation of DCs and CD8+ T-cells." (PMID 37441069, 2023). "RT-PCR was used to analyze the expression of NCX2 and HIF-1α in glioma cell U87MG." (PMID 36334237, 2023). "Furthermore, here we suggest HIF-1α modulation to overcome resistance, as already demonstrated in glioma." (PMID 37407979, 2023). "Therefore, developing inhibitors that targets Nrf2 and HIF-1α would be an effective therapeutic modality to combat glioma." (PMID 37025487, 2023). "Furthermore, HSP47 expression in glioma vessels promotes glioma angiogenesis via HIF1α-VEGFR2 signaling." (PMID 36937386, 2023). "The results of this study also showed that the IVIM parameters could be used to detect HIF-1α expression levels in glioma tissue." (PMID 35785202, 2022). "In addition, a significant positive correlation was observed between R2* and HIF-1α in the glioma model, suggesting that R2* Mapping can be used to detect different levels of glioma tissue oxygenation." (PMID 35785202, 2022). "The CGGA database showed HIF1α and HIF2α expression in glioma." (PMID 34976166, 2022). "Thus, the accurate detection of HIF‐1α expression in glioma facilitates making individual treatment plans, especially regarding the usage of anti-hypoxia drugs." (PMID 35785202, 2022). "Silencing HIF-1α attenuated the enhanced glioma invasion and migration seen with elevated AWPPH." (PMID 36105389, 2022). "We searched for transcription factors that are positively co-expressed with EIF4EBP1 in gliomas and found EIF4EBP1 mRNA expression to be significantly and positively associated with the mRNA expression levels of MYBL2, FOXM1, ETS1, HIF-1A, JUN, E2F1, and E2F6 in the REMBRANDT dataset." (PMID 35228525, 2022). "However, they observed that miR-23b expression was elevated in glioma cells and that miR-23b acted through the HIF-1a/VEGF signaling pathway." (PMID 35682972, 2022). "Moreover, RUNX1T1 reportedly interacts with HIF-1α and recruits proline hydroxylase 2 (PHD2) and GSK3β for HIF-1α degradation, resulting in the inhibition of glioma cells." (PMID 36231060, 2022). "Chromatin immunoprecipitation and luciferase reporter assays have shown direct binding of HIF-1α to a transcriptional hypoxia response element in the PDL-1 promoter, and hypoxia induced PDL-1 overexpression has been shown to be abrogated by a HIF-1α knockdown in glioma cells." (PMID 36077667, 2022). "In addition, Borneolum Syntheticum, commonly known as Borneol, is a bicyclic monoterpenoid reported to mediate apoptotic processes in glioma cells in vitro by overseeing HIF1α expression." (PMID 35409080, 2022). "Some mechanisms for hypoxia-inducing EMT in gliomas have been recognized; for example, VEGF inhibitor therapy will activate c-Met and upregulate Snail and N-cadherin, and HIF-1α can upregulate Zeb2, which will downregulate EphrinB2, an invasion-inhibitory receptor in gliomas." (PMID 36338770, 2022). "The HIF1α/VEGF pathway played an important role in the edema induced by gliomas." (PMID 35955525, 2022).
glioma (continued). "A subsequent study by the same authors has shown that glioma-derived FGL2 induces secretion of PPBP (CXCL7) by a subset of TAMs following activation of FGL2/CD16/PI3K/Akt/HIF1α signalling, which promotes the expression of stem-like properties in glioma cells (Molecular event 23)." (PMID 36555253, 2022). "Interestingly, studies have shown that IDH mutation is associated with elevated levels of HIF-1α and VEGF levels in IDH-mutant gliomas." (PMID 35198082, 2022). "A recent study suggests that HIF-1α expression can be down-regulated by microRNA such as miR-935 in a feedback loop which in turn may inhibit glioma development." (PMID 36014432, 2022). "14-3-3β and HIF-1α may therefore be considered as the potential therapeutic target to treat patients with glioma." (PMID 35607406, 2022). "Multitherapeutic approaches could therefore increase glioma therapeutic efficiency by combining 14-3-3β and HIF-1α inhibitors or siRNA application." (PMID 35607406, 2022). "Increased expression of HIF1α can enhance the hypoxic viability of glioma cells." (PMID 35287356, 2022). "Finally, we focused on the clinical implications of miR-935, because previous studies have shown that miR-935 inhibits proliferation and invasion in glioma through the miR-935/HIF1A regulatory axis." (PMID 35626094, 2022). "However, glioma cells are resistant to silvestrol under hypoxic condition which is related to HIF1α." (PMID 35677890, 2022). "Evidence has shown that several molecules such as Ki-67, epidermal growth factor receptor (EGFR), vascular endothelial growth factor (VEGF), O-6-methylguanine-DNA methyltransferase (MGMT), and hypoxia-inducible factor 1-alpha (HIF-1α) play important roles in the growth of glioma." (PMID 36591483, 2022). "In fact, it has been shown that PPAR-γ inhibition improves CIDEA expression, triggering glioma cell apoptosis and a decrease in HIF-1α activation, justifying further investigations aimed at evaluating the efficacy of PPAR-γ inhibitors as an effective anti-glioma therapeutic strategy." (PMID 35203272, 2022). "To further study whether HIF-1α is an upstream factor related to tau hyperphosphorylation, we employed CoCl2 to induce chemical hypoxia in rat C6 glioma cells stably expressing human full-length tau441 (C6/tau cells)." (PMID 36555780, 2022). "Effective inhibition on HIF-1α using novel inhibitors combined with 14-3-3β knockdown may be considered as a potential therapeutic strategy to treat patients with glioma." (PMID 35607406, 2022). "We were determined to explore whether suppression of HIF-1α could directly induce lipid peroxidation in glioma cells." (PMID 36439690, 2022). "Subsequently, targeted inhibition of HIF-1α or 14-3-3β may provide novel clinical therapeutic strategies to treat patients with glioma." (PMID 35607406, 2022). "Our previous study reported that inhibition on HIF-1α could be important for the biological behavior changes of glioma cells." (PMID 35607406, 2022). "Previous studies have found that HIF 1a and BNIP3L signal pathways play an important role in the pathogenesis of brain diseases such as cerebral ischemia/reperfusion, cerebral hemorrhage, memory ischemia, glioma and Alzheimer’s disease.The expression levels of HIF-1α and BNIP3L are increased." (PMID 36569834, 2022). "Consequently, the levels of OR7E156P and HIF1A were then examined in tissue samples and glioma cell lines in conditions of normoxia and hypoxia." (PMID 34422645, 2021). "Herein, in glioma cells, hypoxia stimulation markedly increased HIF1A expression." (PMID 34422645, 2021). "These 5 miRNAs (miR-17, miR-20a, miR-153, miR-519d, and miR-143-5p) could potentially possess binding sites with OR7E156P/HIF1A, and are negatively correlated with HIF1A in glioma, respectively." (PMID 34422645, 2021). "A network formed by lncRNA OR7E156P, miR-143, and HIF1A that might modulate hypoxia-related glioma growth and metastasis was conclusively demonstrated." (PMID 34422645, 2021).
glioma (continued). "Cav-1-dependent expression of HIF-1α and Akt may be involved in the promotive role of Cav-1 in glioma cell proliferation and VM formation." (PMID 34287575, 2021). "HAX1 regulated by HIF‐1α was increased in glioma cells cultured in hypoxia." (PMID 34755451, 2021). "HIF‐1α was discovered to improve the expression of HAX1 in glioma cells cultured in hypoxia." (PMID 34755451, 2021). "Notably, we found that the TNFRSF14 (HVEM) level was higher in low-HIF1A-expression lower-grade glioma." (PMID 34305618, 2021). "Furthermore, ChIP-qPCR analysis showed the direct binding of HIF-1α to PD-L1 proximal promoter region, providing evidence that HIF-1α up-regulates PD-L1 in glioma." (PMID 34118979, 2021). "EGLN1 knockdown comprised the proliferation of IDH1mt astrocyte while downregulating HIF-1α did the opposite; these results suggest that IDHmt-derived D-2HG activates EGLN1, and subsequent downregulation of HIF-1α may lead to the tumorigenesis of glioma." (PMID 33842477, 2021). "In addition, BCA treatment significantly inhibits the Warburg effect in U251 human glioma cells by regulating HIF-1a expression through the inactivation of the AKT/mTOR pathway." (PMID 34307130, 2021). "Mutated IDH blocks the differentiation of glioma stem cells by forming an increased amount of 2-hydroxyglutaric acid, regulating VEGF, that promotes tumor microenvironment, and also forms the increased HIF-1α leading to glioma invasion." (PMID 34199460, 2021). "We used the well-known HIF1α inducer cobalt chloride (CoCl2) to imitate hypoxia in glioma cells." (PMID 33546324, 2021). "VEGF/Akt/surviving and HIF-1α/MMP-2 pathways might be involved in canstatin-inhibited VM formation in U87 glioma cells." (PMID 34434564, 2021). "Similarly, in patients with GBM and lower-grade glioma, we found that high-HIF1A-expression tumors expressed higher levels of PDL1." (PMID 34305618, 2021). "Furthermore, in vitro migration assays of glioma-produced HIF-1α KO Tregs showed an inhibited migratory response to CCL22 chemotactic agent in GL-261 murine glioblastoma model." (PMID 33532902, 2021). "Thus, the treatment of ex vivo expanded human γδ T cells with metformin or HIF-1α inhibitor showed roughly 75% tumor-free survival in the glioma xenograft model." (PMID 34831116, 2021). "In addition, we made comparisons of HIF1A expression in lower grade glioma grouped by IDH and 1p/19q codeletion status in the two datasets." (PMID 34305618, 2021). "Thus, borneol sensitizes glioma cells to radiation by inducing autophagy via the inhibition of the mTORC1/eIF4E/HIF-1A pathway." (PMID 34917504, 2021). "HIF-1α has been proposed to drive glioma progression from low-grade astrocytoma to high-grade GBM." (PMID 33842321, 2021). "Altogether a regulatory axis consisting of OR7E156P, miR-143, and HIF1A, was identified which is deregulated in glioma, and the process of the OR7E156P/miR-143/HIF1A axis modulating glioma cell invasion through ZEB1 and HUVEC tube formation through VEGF was demonstrated." (PMID 34422645, 2021). "Moreover, exposure to hypoxia produced a significant expression of CXCR4 and HIF-1α in glioma cells, while VEGF stimulated angiogenic response of CXCR4 in normal endothelial cells from brain microvessels." (PMID 34200145, 2021). "Based on these studies, inhibition of HIF-1α may be a good strategy to suppress the growth of IDH-mutant gliomas." (PMID 34356864, 2021). "Many molecules also regulate the characteristics of glioma in a hypoxic environment by HIF‐1α." (PMID 34755451, 2021). "Furthermore, the combination of borneol and radiation exposure significantly decreased the expression levels of HIF-1α, mTORC1 and eIF4E proteins in the glioma cells compared to the untreated controls (p < 0.05 or p < 0.01)." (PMID 34917504, 2021). "Furthermore, they showed that under normoxic conditions, knocked-down HIF-1α glioma cells had a lower migration capacity than control cells." (PMID 34830491, 2021).
glioma (continued). "Investigating the specific role of HIF1A in T-cell exhaustion in gliomas is an important issue, which could help to improve the efficacy of immunotherapy." (PMID 34305618, 2021). "Baicalein affected HIF-1α expression in glioma and ovarian cancer cells." (PMID 33401572, 2021). "CGGA database showed that both HIF1α and HIF2α were highly expressed in glioma tissues." (PMID 33986256, 2021). "Taken together, hypoxia may potentially regulate TMZ resistance in glioma cells through the HIF-1α/Shh/GLI1 axis." (PMID 34638233, 2021). "miR-143 inhibition increased HIF1A protein levels, promoted glioma cell invasion and DNA synthesis." (PMID 34422645, 2021). "PDIA3P1 upregulation in hypoxia-cultured glioma cells was reversed when HIF1A was inhibited." (PMID 32127518, 2020). "Therefore, it can be concluded that rapid proliferation of glioma cells triggers hypoxia within the tumor cells, activating downstream genes including HIF‐1α and Prox1 and leading to tumor cell differentiation and expression of LYVE‐1." (PMID 31960509, 2020). "Furthermore, Pearson’s correlation analysis showed a positive correlation between MCT4 and HIF-1α expression levels in glioma patients." (PMID 32045997, 2020). "In conclusion, the findings of the present study suggest that HIF-1α may be a key factor in borneol induced apoptosis of glioma cells, and mTORC1 / eIF4E pathway is involved in the HIF-1α regulation by borneol in malignant glioma." (PMID 32626528, 2020). "By examining the hypoxia-related miRNAs in glioma, researchers have shown that miR-210-3p may be related to tumour growth through a HIF1α-dependent mechanism." (PMID 33208727, 2020). "However, HIF‐1α expression was significantly increased in glioma tissues compared with normal brain tissues." (PMID 31960509, 2020). "Finally, Pearson’s correlation analysis also showed a positive association between HIF-1α and CAIX expression levels in the gene expression dataset of patients with glioma." (PMID 32823915, 2020). "Interestingly, another study illustrated that circDENND2A was induced by hypoxia in glioma cells, and the circDENND2A-miR-625-5p axis promotes invasion and migration in glioma cells via the miR-625-5p interacted with HIF1α." (PMID 32467668, 2020). "The density of TAMs increased in higher grade gliomas and in hypoxic HIF-1α-positive regions." (PMID 32486098, 2020). "Moreover, the upregulation of miRNA-199a-3p in exosomes from glioma cells was induced by hypoxia-related HIF-1α activation." (PMID 33110474, 2020). "HIF‐1α+ Prox1+ cells were widely distributed within the glioma specimens." (PMID 31960509, 2020). "In tissue, the so called pseudopalisades are known to be rich in HIF-1α, carbonic anhydrase IX and MMPs and may be considered an invading front of aggressive glioma tumours." (PMID 33057069, 2020). "To further determine the mechanism by which hypoxia induced FTL expression, we treated U87 and U251 cells with cobalt chloride (CoCl2,400 mM) for 24 h.The results showed that inhibition HIF1A degradation dramatically promoted the expression of FTL in glioma cells." (PMID 32677981, 2020). "Then, we found that eIF4E siRNA suppressed the expression of HIF-1α, whereas the expression of eIF4E was inhibited by the mTORC1 siRNA, suggesting that the mTORC1/eIF4E pathway participates in regulating the expression of HIF-1α in primary human glioma culture cells under hypoxia." (PMID 32626528, 2020). "Moreover, consistent with our study, researchers identified that miR‐148a was an oncogenic gene associated with glioma survival and affected EGFR activation or regulated glioma growth by mediating HIF1α and Notch signalling." (PMID 32412186, 2020). "In conclusion, the findings of the present study suggest that HIF-1α may be a key factor in apoptosis of glioma cells, and mTORC1/eIF4E pathway is involved in the HIF-1a expression regulation by borneol in malignant glioma." (PMID 32626528, 2020).
glioma (continued). "The lncRNA H19 promotes angiogenesis in glioma via the miR-138/HIF1α/VEGF axis." (PMID 33126510, 2020). "The density of positive HIF-1α staining was higher in tumoral areas than in normal parenchyma, which confirmed the existence of hypoxia in glioma and its surrounding parenchyma and also suggested that glioma cells were growing within and around hypoxic environments." (PMID 33110474, 2020). "As the microenvironment is known to influence gene expression, e.g., the hypoxia-stimulated HIF-1α expression in glioma or the culture mode (2D vs. 3D)-dependent differential gene expression of colorectal cell lines, we further investigated the expression of sig1R in the intracerebral U87-MG tumour." (PMID 32384802, 2020). "HIF1α activation would allow for the adaptation of glioma cells to hypoxia and survival." (PMID 30082910, 2019). "Glioma EV mediated transfer of HIF-1α promotes radioresistance in sensitive glioma cells." (PMID 32038644, 2019). "The U87-MG gliomas expressed HIF-1α at higher levels and more uniformly than the 9L gliosarcomas." (PMID 30837601, 2019). "ELTD1 promotes the progression of glioma through the JAK/STAT3/HIF-1α axis." (PMID 31554859, 2019). "Hypoxic IR-resistant cells tend to spread, often resulting in relapse after treatment, therefore inactivation of Hif-1α could have a significant therapeutic response in glioma." (PMID 31632280, 2019). "Regulation of HIF-1α stability with small metabolites has also been demonstrated in glioma." (PMID 31225497, 2019). "Overexpression of HIF1α leads to tumor progression and poor prognosis in patients with glioma." (PMID 30988674, 2019). "The characters of low oxygen level in glioma cells could enhance some hypoxia-inducible factors, including mainly Hypoxia-inducible factor 1-alpha (HIF-1α)." (PMID 31450822, 2019). "Since PHD3 is the downstream target of miR-9, we speculated that the canonical HIF-1α/VEGF signaling pathway is involved in regulating glioma angiogenesis." (PMID 30795814, 2019). "However, the crosstalk between HIF1α and the circDENND2A/miR-625-5p pathway in glioma still needs more investigation." (PMID 30988674, 2019). "In addition, IDH mutations can also induce high levels of hypoxia-inducible factor-1α (HIF-1α) to promote glioma invasion." (PMID 31263678, 2019). "The overexpression of HIF1α was also well described in glioma." (PMID 30082910, 2019). "Based on the findings, we propose that STAT6 downregulation resulting from DNA methyltransferase (DNMT)-mediated hypermethylation of promoter CpG islands facilitates accumulation of HIF-1α through mTOR activation in hypoxia and consequent enhancement of glioma cell survival." (PMID 31530290, 2019). "Therefore, the PHD3-mediated HIF-1α/VEGF signaling pathway is engaged in the regulation of glioma tumorigenesis and is particularly vital for tumor neovascularization." (PMID 30795814, 2019). "Notably, glioma tissues overexpressing HIF1α exhibited a high expression of circDENND2A as well as a low expression of miR-625-5p." (PMID 30988674, 2019). "Immunohistochemistry was performed to analyze the HIF1α level in glioma tissues." (PMID 30988674, 2019). "Knockdown of HIF-1α expression increases sensitivity of glioma to TMZ treatment." (PMID 30262908, 2018). "However, other studies have reported unchanged or lower HIF-1α levels in IDHmut gliomas relative to IDHwt." (PMID 29619216, 2018). "HIF1α and HIF2α are good targets for glioma and glioma CSCs." (PMID 30310855, 2018). "Additionally, the expression of MCT1 in the plasmatic membrane has been associated to HIF-1α in hypoxic areas of GBM tumors, and the inhibition of MCT1 by drugs reduced the viability, proliferation, and migration of U251 glioma cells." (PMID 30486451, 2018). "Additionally, HIF1α and HIF2α were shown to be responsible for acquiring stem cell properties in differentiated glioma cells." (PMID 30510501, 2018).